IL21 (interleukin 21)
Diseases named in the same sentence as IL21 in open-access papers (continued):
Sharing a sentence is not in itself a finding about the gene and the disease.
colitis (54 papers, 2011 to 2025). Inflammation of the colon. "In both inflammatory bowel disease (IBD) patients and dextran sodium sulfate (DSS)-induced colitis models, elevated interleukin-21 (IL-21) levels are associated with Cldn5 downregulation, mediated by upregulation of miR-423-5p." (PMID 40940757, 2025). "Around 90% of DKO mice at 20 weeks of age were resistant to diarrhea and did not exhibit weight loss whereas only 30% of CKO mice were diarrhea free at the same age, further validating the pathogenic role of IL-21 in Blimp-1 deficiency–induced colitis." (PMID 35503415, 2022). "As well, we show that neutralization of IL-21 in experimental T cell-driven colitis is associated with a reduction in clinical and pathological findings." (PMID 29849593, 2018). "Collectively, Th17 cell cytokines IL-21 and IL-22 have tumor-promoting effects in colitis-associated CRC." (PMID 28852270, 2017). "In a very similar model, Fichtner-Feigl’s group showed that IL-21 promotes colitis-related CRC and associated this effect with increased tumor cell proliferation and impaired anti-tumor response of CD103+ CD8+ cytotoxic T cells specific for cancer cells." (PMID 23109839, 2012). "High levels of IL-21 have been observed in the gut of patients with UC-associated colon cancer and in mice with colitis-associated CRC induced by AOM + DSS." (PMID 23109839, 2012). "In this model, IL-21-deficient mice developed a less severe colitis than wild-type mice, characterized by reduced mucosal damage, reduced infiltration of T cells, and diminished production of IL-6 and IL-17A." (PMID 23109839, 2012). "Using a mouse model of HFD + trinitrobenzene sulfonic acid (TNBS)-induced colitis, dietary n-3 PUFAs have been shown to reduce colitis-associated disease severity and colonic mRNA expression of cytokines (IL-6, IL-17A, IL-17F, IL-21, IL-23, and IFNγ) versus corn oil in control HFD mice." (PMID 40219010, 2025). "Thus, IL-21-deficient mice were protected from colitis through the reduction of Th17 and Th1 as well as MIP-3a/CCR6 interactions displaying the attraction of pathogenic Th17 cells into inflamed tissues." (PMID 33924897, 2021). "The underlying mechanism of IL-21 signalling in experimental colitis is still unclear." (PMID 29849593, 2018). "IL-21 was found overexpressed in patients with UC and colitis-associated CRC." (PMID 28852270, 2017). "The role of IL-21 in colitis-associated CRC has been investigated." (PMID 28852270, 2017). "Moreover, by a comparative analysis of CREMα and wild-type (WT) mice in an experimental colitis model, which is associated with T cellular IL-21 production, we wanted to study the consequences of CREMα-induced cytokine alterations." (PMID 28066428, 2016). "In addition to the blockade of IL-21 by IL-21R.Fc neutralization, we further explored the effects of genetic disruption of IL-21 signaling on Blimp-1 deficiency–mediated colitis by crossing IL-21R–deficient mice with Blimp-1 CKO mice to generate a double-knockout (DKO) mouse model." (PMID 35503415, 2022). "In addition, the HF-FO diet reduced both colitis-associated disease severity and colonic mRNA expression of the Th17 cell master transcription factor (RORγτ) and critical cytokines (IL-6, IL-17A, IL-17F, IL-21, IL-23 and IFNγ) versus HF (P<0.05)." (PMID 23166761, 2012). "In this study, a previously less-defined function of the IL-21/IL-21R signaling in the regulation of colitis through interaction with the IL-12/IL-12Rβ2 signaling was identified." (PMID 38498592, 2024). "The antibody-mediated abrogation of IL-21/IL-21R signaling led to the impaired expression of IFN-γ by mucosal CD4+ T cells from human subjects with colitis, suggesting an IL-21/IL-21R–triggered positive feedback loop of the TH1 immune response in the colon." (PMID 38498592, 2024).
colitis (continued). "Using a well-established and physiologically relevant murine model of Citrobacter rodentium–induced colitis, the mechanisms by which the IL-21/IL-21R signaling axis regulates colitis by enhancing the IL-12 responsiveness of CD4+ T cells were explored." (PMID 38498592, 2024). "Further studies are required to identify the exact contribution of IL-12Rβ1 and IL-12Rβ2 in mediating the proinflammatory functions of IL-21/IL-21R signaling during colitis." (PMID 38498592, 2024). "Neutralization of IL-21 ameliorates clinical and pathological findings primarily in experimental T cell-driven colitis." (PMID 36519841, 2023). "Elevated Th17 cells are associated with the pathogenesis of inflammatory bowel disease (IBD) and colitis through expressing rorγt, IL-17A, IL-17F, and IL-21 in the inflamed mucosa." (PMID 37344888, 2023). "As previously discussed (under DSS colitis), IL-23 synergises with IL-17, IL-21, and IL-22 to drive colon inflammation in the event of defective immune regulation mechanisms." (PMID 36012618, 2022). "An increased accessibility of Il21 promoter is observed in CKO CD4+ T cells, and severity of Blimp-1 deficiency–mediated colitis can be restored by histone acetyltransferase CBP/p300 inhibitor." (PMID 35503415, 2022). "Our data demonstrate that Blimp-1 serves as a gatekeeper in a feedback loop to counterbalance IL-21 secretion in response to the autoimmune processes of colitis and T1D." (PMID 35503415, 2022). "IL-21 facilitates colitogenic phenotypes in UC, and IL-21−/− knockout mice are protected against chemical-induced colitis." (PMID 36142193, 2022). "The infection elevates TGF-β but lowers the IL-17A, IL-17F, IL-6, IL-21, and IL-23 levels, thus likely affecting the immunosuppressive Treg balance across the colon environment in the colitis model." (PMID 33924897, 2021). "Although the proinflammatory effects of IL-21 in IBD have been extensively studied, some studies have shown that IL-21 improves DSS-induced colitis." (PMID 33553436, 2021). "The inflammatory factors IL-21, IL-17 A, IL-6 were up-regulated significantly in colitis model group in contrast to control, while miRNA-182-5p inhibitor alleviated the increase of IL-21, IL-17 A, and IL-6." (PMID 34623552, 2021). "These microscopic and biochemical observations also confirmed the results of gene expression analysis of pro-inflammatory cytokines in colon tissue affected by colitis, including Ifng and Tnf after 3 days and Il21 after 21 days." (PMID 33499397, 2021). "In this stage of colitis, food intake with βGh (CβGh+ group) up-regulated the expression of the Il13, Il21, Il27, and Lta genes and down-regulated the expression of the Il1a, Il11, and Il17a genes." (PMID 33923129, 2021). "We found that mice treated with IL-21 neutralizing antibody had a protective effect on experimental colitis compared with the DSS group." (PMID 32855360, 2020). "Anti-IL-21 administrated prevented DSS-simulative colitis via recovering claudin-5 expression in the human colonic epithelial cells." (PMID 32855360, 2020). "Surprisingly, the levels of the proinflammatory cytokine IL-21 were lower in the colitis mice than in the normal group of mice." (PMID 33597887, 2020). "DSS colitis and TNBS-relapsing colitis are significantly decreased in IL-21-deficient mice, which is associated with reduced expression of Th17 cell-related genes (IL-17, IL-17F, and RORγt) in the colon tissue." (PMID 31886308, 2019). "Elevated levels of IL-6, IL-23, and IL-17 have been found in serum and colon mucosa of patients with UC, IL-23 exacerbates colon inflammation, and blocking IL-23 or IL-21 ameliorates colitis in mice, demonstrating that Th17 cells are key effector cells in UC." (PMID 31534467, 2019). "We also demonstrate that IL-21 neutralization only is efficacious in models with CD4 T cell-driven colitis and primarily affects homing of calprotectin-positive cells." (PMID 29849593, 2018).
colitis (continued). "The pathologic role of IL-21 was examined in murine models of T cell-dependent and T cell-independent colitis, either with a neutralizing monoclonal antibody against IL-21 or with the transfer of CD4+CD45RBhighIL-21R−/− T cells." (PMID 29849593, 2018). "Exposure from AdTr colitis mice using two selected doses of mouse anti-mouse IL-21 (3.3 mg/kg and 25 mg/kg) was compared with the simulated exposure levels based on pharmacokinetics in healthy NMRI mice." (PMID 29849593, 2018). "Because IL-21 is reported to be produced by both human and mouse Th17 cells and since Th17 cells have been shown to be involved in adoptive transfer colitis, we initially focused on the CD4+CD25− T cell transfer model of colitis." (PMID 29849593, 2018). "To elucidate the roles of IL-21/IL-21R signaling in DSS-induced colitis, we examined the effect of in vivo administration of rIL-21 on DSS-induced intestinal inflammation in C57BL/6 mice." (PMID 27545302, 2016). "Here, we analyzed CREMα tg T cells and IL-21 expression of these T cells within an acute model of murine colitis." (PMID 28066428, 2016). "Our results demonstrate that IL-21/IL-21R signaling contributes to protection against DSS-induced acute colitis through suppression of Th1 and activation of Th2, Th17 and Treg responses in mice." (PMID 27545302, 2016). "In line with this, our data have shown that IL-21/IL-21R signaling protects mice from DSS-induced colitis through regulation of Th cell-mediated immune responses in intestinal mucosa." (PMID 27545302, 2016). "It has been demonstrated that a deficiency in CD69 leads to increased production of pro-inflammatory cytokines (such as TNF-α, IFN-γ, and IL-21), reduced FoxP3+ regulatory T-cell function, impaired oral tolerance, and more severe colitis." (PMID 26206376, 2015). "IL-21-deficient mice are largely protected against DSS- and TNBS-colitis, and this protection is associated with a marked decrease in IL-17A and IL-17F, thus confirming the key role of IL-21 in sustaining Th17 immunity." (PMID 22082127, 2011). "A better understanding of the novel mechanisms by which IL-21/IL-21R signaling regulates bacterial-induced colitis will provide insights into the development of new therapeutic and preventive strategies to harness IL-21/IL-21R signaling or its downstream molecules to treat infectious colitis." (PMID 38498592, 2024). "Predicted upstream regulators of ILCs in CPI-C included Tbx21, encoding the transcription factor T-bet, and genes encoding the cytokines Il2, Il18 and Il21, suggesting that ILC1 may contribute to colitis in this model." (PMID 39496592, 2024). "For example, the adoptive transfer of CD69-deficient CD4+ T cells into RAG-/- mice (deficient in lymphocytes) induced severe colitis due to the increased secretion of proinflammatory cytokines (IFN-γ, TNF-α, IL-21) and decreased levels of anti-inflammatory cytokines (TGF-β1)." (PMID 39451246, 2024). "While the cascade of events leading to the activation of STAT3 by IL-21 has been extensively studied, it is unclear how the events downstream of IL-12Rβ2 signaling affect the expression of proinflammatory gene profiles during colitis." (PMID 38498592, 2024). "Increased levels of IL-21 have been found in mice with chronic DSS-induced and TNBS-induced colitis, and IL-21 blockade by the addition of neutralizing IL-21R fusion proteins to DSS-treated mice mitigates colitis and inhibits the release of the main Th17 cytokines." (PMID 36769019, 2023). "Interestingly, IL-21 signalling was recently proposed to dampen T-cell transfer colitis by reducing IL-17A production and augmenting IL-22 production in populations of ILC3s." (PMID 36012618, 2022). "We observed a negative relationship between Blimp-1 and IL-21 based on our previous data that Blimp-1 overexpression in T cells suppresses autoimmune diabetes while Blimp-1–deficient T cells contribute to colitis in NOD mice." (PMID 35503415, 2022).
colitis (continued). "IL-21 knockout (IL-21KO) mice were resistant to dextran sulphate sodium- (DSS-) induced colitis." (PMID 34471409, 2021). "Anti-IL-21 mAb treatment also ameliorated CD4+CD25− T cell adoptive transfer (AdTr) Colitis." (PMID 34471409, 2021). "We will explore the role played by IL-21 in DSS-induced colitis by knocking out the IL-21 gene." (PMID 33597887, 2020). "Still, in most studies, IL-21−/− mice have been reported to be protected from DSS-induced colitis." (PMID 29849593, 2018). "In addition, mesLN CD4+ T cells isolated from mice with colitis responded with excessive production of proinflammatory cytokines and chemokines following stimulation with exogenous IL-21." (PMID 29849593, 2018). "As well, the percentage of mesLN IL-21+CD4+ cells correlated with the degree of body weight change in individual mice with colitis, indicating that IL-21 may be involved in colonic disease development in this model." (PMID 29849593, 2018). "Still, the percentage of IL-21+CD4+ T cells was lower compared to the AdTr colitis model." (PMID 29849593, 2018). "Moreover, before treatment, studies were initiated; target validation was conducted to describe the dynamics of IL-21 protein expression by CD4+ T cells during the development of colitis." (PMID 29849593, 2018). "Next, we wanted to assess whether treatment with 25 mg/kg anti-IL-21 mAb could prevent adoptive transfer colitis, compared to mice treated with mIgG1." (PMID 29849593, 2018). "Previous studies have shown that mice lacking IL-21 are unable to upregulate Th17-associated molecules during experimental colitis and are largely protected from DSS-induced colitis." (PMID 29849593, 2018). "Anti-IL-21 mAb treatment was also evaluated in the piroxicam-accelerated colitis (PAC) mouse model." (PMID 29849593, 2018). "Finally, this is of functional relevance since CREMα transgenic mice display enhanced disease activity in dextran sodium sulfate-induced colitis accompanied by higher local IL-21 expression." (PMID 28066428, 2016). "With this regard, it is not surprising that mice lacking IL-21 are unable to upregulate Th17-associated molecules during experimental gut inflammation and are largely protected against chemically induced colitis." (PMID 28066428, 2016). "Our data suggest that CREMα might be involved in IL-21 secretion of T cells in DSS-colitis as was shown before in a contact dermatitis model." (PMID 28066428, 2016). "Recent studies from our laboratory have shown that IL-21 is highly expressed in the mucosa of patients with ulcerative colitis complicated by CRC, and also plays a key role in sustaining the growth of cancer cells in mice with colitis-associated CRC." (PMID 25839161, 2015). "Like human IBD, mice with acute DSS-colitis and TNBS-relapsing colitis produce elevated levels of IL-21, and administration of a neutralizing IL-21R fusion protein to DSS-treated mice attenuates the ongoing colitis and reduces the production of Th17-related cytokines." (PMID 22082127, 2011). "Despite recent advances in our understanding of the mechanisms underpinning the regulation of proinflammatory immune responses by the IL-21/IL-21R signaling axis, it remains unclear how this pathway or its downstream molecules contribute to inflammation during bacterial-induced colitis." (PMID 38498592, 2024). "However, IL-21 may play a protective role in the DSS-induced colitis model through its induction of IL-22, a member of the IL-10 family that promotes tissue regeneration and repair." (PMID 36519841, 2023). "Using a murine model of Citrobacter rodentium infection, we found the requirement of a functional IL-21/IL-21R signaling axis in the control of enteric microbial infections via augmenting activation of STAT1 in mucosal CD4+ T cells in a murine model of Citrobacter rodentium colitis." (PMID 30818341, 2019).
colitis (continued). "The discrepancy between colitis studies with IL-21 or IL-21R−/− mice may be due to variability in microflora between laboratories, T cell dependency in the model setup, or a consequence of transcriptional changes in the areas around the targeted gene in the k.o. mice." (PMID 29849593, 2018). "Furthermore, mice lacking IL-21 are unable to upregulate Th17-associated molecules during experimental gut inflammation and are largely protected against chemically induced colitis." (PMID 28066428, 2016). "It was also reported on experimental model of colitis-associated colorectal carcinoma, that NFATC2-deficient mice were protected from tumor development and show significantly reduced levels of the downstream critical proinflammatory cytokines interleukin IL21 and IL6." (PMID 24416320, 2014). "The findings of the current study provide novel insights into the mechanisms by which functional IL-21/IL-21R signaling regulates IL-12 responsiveness by promoting IL-12Rβ2 expression in CD4+ T cells, leading to colitis." (PMID 38498592, 2024). "The findings of the current study indicated that murine hosts lacking the IL-12/IL-12Rβ2 axis downstream of IL-21/IL-21R signaling and their littermate controls were equally susceptible to colon infection, yet Il12rb2−/− mice exhibited attenuated C. rodentium–induced colitis." (PMID 38498592, 2024). "The serum level of IL-21 in CKO mice with severe colitis was significantly higher than that in age-matched diarrhea-free CKO mice, indicating the critical role of IL-21 as a driving force in the colitogenic process in CKO mice." (PMID 35503415, 2022). "The deficiency of CXCL13 resulted in significantly decreased expression of inflammatory cytokines IL-21, IL-1β, IL-1α, IL-17, IL-6 and TNF-α in colon sites of mice with colitis." (PMID 36172372, 2022). "Blockade of IL-21 by administration of a neutralizing IL-21 antibody decreased the colonic infiltration of Tfh cells and inhibited development of DSS-induced colitis." (PMID 34471409, 2021). "In a mouse model of colitis, CUR treatment decreased the expression of TNF-α, IL-2, IL-6, IL-12 p40, IL-17, and IL-21 to a level comparable to healthy mice." (PMID 32423101, 2020). "For further research, we established a C57BL/6 mouse model of acute colitis with DSS and treated it with IL-21 neutralizing antibody." (PMID 32855360, 2020). "The data in this paper revealed that the expression levels of IL-17, IL-21, IL-23, IL-6, IL-1β, TNFα, and IL-12 in mLN tissues significantly decreased in CD169-DTR colitis mice compared to those in WT colitis mice." (PMID 28694804, 2017). "Mice deficient for the TH17 subset-associated pro-inflammatory cytokine IL-21 were consequently protected against the development of DSS colitis and failed to up-regulate other critical TH17-associated molecules such as IL-17 and ROR-γt, which could be confirmed in the TNBS-induced colitis model." (PMID 23874340, 2013). "To further determine which TH17 cytokines are responsible for inhibiting chemokine expression and protect the Tak1ΔM/ΔM mice against colitis and CRC, we performed intracellular staining of key TH17 cytokines (IL-17A, IL-17F, IL-21, and IL-22) in CD4+ cells from intestinal LP." (PMID 40749055, 2025). "UC patients displayed excessive IL-21 in mucosal samples, leading the colonic epithelial cells to produce the macrophage inflammatory protein (MIP)-3a (also called CCL20), a chemokine upregulated in IBD patients or mice with chemically induced colitis." (PMID 33924897, 2021). "IL-21 also promotes IL-22 expression in mucosal T-cells through a mechanism involving STAT3, retinoid-related orphan receptor γt, and aryl hydrocarbon receptor, thereby helping protect immunodeficient mice from DSS colitis." (PMID 32855621, 2020). "Similarly, IL-21 was highly expressed in the colons of C57BL/6 mice with dextran sulfate sodium (DSS)-induced colitis and Il21r-/- mice manifested milder DSS-induced colitis as compared with their WT counterparts." (PMID 30818341, 2019).